THPO (thrombopoietin)
Description:
Lineage-specific cytokine affecting the proliferation and maturation of megakaryocytes from their committed progenitor cells. It acts at a late stage of megakaryocyte development. It may be the major physiological regulator of circulating platelets.
Synonyms: ML; MGDF; TPO; MPLLG; CAMT2; MKCSF; THC9; THCYT1
Tractability: Small molecule: it belongs to a druggable protein family. Antibody: UniProt places it where antibodies can reach, with high confidence; UniProt predicts a signal peptide or a membrane-spanning region; its Gene Ontology location is reachable by antibodies, with medium confidence. PROTAC: a small molecule that binds it is known.
Target class: Secreted protein
Gene: Protein-coding gene on chromosome 3 (184,371,935 to 184,381,968, reverse strand). Ensembl gene ENSG00000090534.
Subcellular location: Secreted
Pathways (Reactome):
Hemostasis: Platelet Aggregation (Plug Formation)
Gene Ontology:
Molecular function: cytokine activity; protein binding; growth factor activity; signaling receptor binding; hormone activity
Biological process: cell surface receptor signaling pathway via STAT; megakaryocyte development; megakaryocyte differentiation; positive regulation of cell population proliferation; positive regulation of hematopoietic stem cell proliferation; positive regulation of MAPK cascade; positive regulation of phosphatidylinositol 3-kinase/protein kinase B signal transduction; regulation of hemopoiesis; thrombopoietin-mediated signaling pathway; positive regulation of ERK1 and ERK2 cascade; positive regulation of megakaryocyte differentiation; positive regulation of protein phosphorylation; cell population proliferation
Cellular component: extracellular region; receptor complex
Genetic constraint (gnomAD): Loss-of-function variants: 13 observed, 18.51 expected, observed/expected ratio (o/e) 0.7, 90% interval 0.46 to 1.12. The upper end of that interval is the gene's LOEUF score, 1.12, which puts it in group 4 of 6, group 1 being the genes least tolerant of losing a copy. Missense variants: 365 observed, 449.77 expected, observed/expected ratio (o/e) 0.81, 90% interval 0.74 to 0.88. Synonymous variants: 188 observed, 192.79 expected, observed/expected ratio (o/e) 0.98, 90% interval 0.87 to 1.1.
Gene-disease validity (ClinGen):
ClinGen rates the evidence that THPO causes each of these diseases.
congenital amegakaryocytic thrombocytopenia (semidominant): Definitive.
thrombocythemia 1 (autosomal dominant): Definitive.
Homologues: Orthologues: chimpanzee THPO (100% identical), macaque THPO (97% identical), dog THPO (76% identical), pig THPO (75% identical), rabbit THPO (72% identical), mouse Thpo (71% identical), rat Thpo (69% identical), zebrafish thpo (10% identical).
Diseases named in the same sentence as THPO in open-access papers:
THPO is named in the same sentence as 145 diseases in open-access papers, as found by Europe PMC text mining. Sharing a sentence is not in itself a finding about the gene and the disease. The quoted sentences say what the papers report.
Thrombocytopenia (200 papers, 2009 to 2026). A reduction in the number of circulating thrombocytes. "As in neonatal sepsis, thrombocytopenia associated with classical NEC is thought to result from excessive production of thrombopoietin, driving functional “exhaustion” of the bone marrow." (PMID 40201118, 2025). "Successful development of thrombopoietin agonists appeared promising especially in other conditions associated with thrombocytopenia but its utility in MDS has been controversial." (PMID 40935929, 2025). "In our patient, thrombocytopenia recurred after eltrombopag discontinuation and improved upon reintroduction, consistent with bone marrow hypoplasia associated with cirrhosis and thrombopoietin deficiency." (PMID 41409974, 2025). "In some other instances, thrombocytopenia in patients with AN is reportedly caused by decreased thrombopoietin production in the liver due to severe liver dysfunction." (PMID 38702806, 2024). "The two main causes of thrombocytopenia in liver illness are decreased platelet production as a result of decreased thrombopoietin production and splenic sequestration." (PMID 39859975, 2024). "After presenting to our clinic, following the exclusion of the common causes of late presenting persistent thrombocytopenia, a partial loss of function in exon 6 of the THPO gene was detected via whole-genome sequencing." (PMID 39479124, 2024). "Platelet sequestration in the spleen and reduced hepatic thrombopoietin production are the main causes of thrombocytopenia in liver cirrhosis." (PMID 39859975, 2024). "THPO gene mutations cause CAMT2 to manifest in early infancy as thrombocytopenia with hypoplastic bone marrow and decreased or normal serum THPO levels, with later progression to bone marrow failure." (PMID 39479124, 2024). "Thrombocytopenia was caused by an increase in platelet destruction and reduced thrombopoietin due to the usage of DFP chelation and hypersplenism, which has a 10% incidence rate of bleeding." (PMID 39231181, 2024). "It is important to exercise caution when using Thrombopoietin in the treatment of glycoprotein IIb/IIIa receptor antagonists introduced thrombocytopenia, considering the possible risk of thrombosis." (PMID 37960787, 2023). "Therapeutic targets for managing sepsis-associated thrombocytopenia include IL-11 and recombinant human thrombopoietin, which have shown promising results in improving platelet counts." (PMID 37841241, 2023). "In COVID-19, thrombocytopenia caused by excessive consumption and destruction leads to a compensatory increase in thrombopoietin, and bone marrow megakaryocytes increase with focal clustering for active platelet production." (PMID 37020458, 2023). "Previously, variants in the 5′ UTR of THPO have been reported as causative variants associated with thrombocytosis, whereas variants in its receptor-binding domain are associated with thrombocytopenia." (PMID 36534659, 2022). "A review of the medical history revealed that the patient had inherited thrombocytopenia with a THPO variant and showed megakaryocytic hypoplasia." (PMID 36534659, 2022). "Recombinant human thrombopoietin (rh-TPO) is generally used for treating thrombocytopenia caused by chemotherapy and immune thrombocytopenia." (PMID 36267268, 2022). "Depending on the location of the variant in THPO, patients with THPO variants show variable clinical symptoms, ranging from thrombocytosis to thrombocytopenia." (PMID 36534659, 2022). "Thrombocytopenia can also be caused by a decrease in thrombopoietin (a regulator of megakaryopoiesis and platelet production) following damage caused to hepatocytes in SARS-CoV-2 infection." (PMID 35207365, 2022). "By sequential sampling and family study of multigene target sequencing, the current study strongly suggests that the identified variant of the THPO gene manifested as thrombocytopenia and subsequently led to leukemic progression." (PMID 36534659, 2022).
Thrombocytopenia (continued). "The study has an established total of 708 patients with sepsis-associated thrombocytopenia and will undergo recombinant human thrombopoietin or placebo (in a 1:1 ratio)." (PMID 35774677, 2022). "Of the three patients, one progressed from megakaryocytic hypoplasia with thrombocytopenia, and targeted multigene sequencing revealed THPO variants in this patient and his sister." (PMID 36534659, 2022). "We measured parasite burden, blood parameters associated with anemia and thrombocytopenia, and serum thrombopoietin." (PMID 34286101, 2021). "An ENU mutagenesis screen was performed to identify mutations that ameliorate thrombocytopenia in Mpl−/− mice via thrombopoietin independent platelet production." (PMID 32561755, 2020). "Several biomarkers were evaluated to determine a causative factor for the depth and duration of thrombocytopenia noted, including evaluation of Immunoglobulin G (IgG) antibody and thrombopoietin (TPO) levels." (PMID 30132271, 2019). "Thrombocytopenia has been attributed to thrombopoietin deficiency in advanced liver disease and possible increased destruction of platelets due to hypersplenism among other mechanisms." (PMID 31783802, 2019). "Although debatable, thrombocytopenia causes a physiologic compensatory secretion of thrombopoietin that seems to correlate with other prognostic biomarkers including IGHV mutation status, ZAP 70 and CD38." (PMID 30450231, 2018). "In the future, it will be critical for any patients with aplastic anemia and preceding thrombocytopenia to be screened for THPO mutations, as this condition can be readily reversed with clinically available MPL agonists." (PMID 29191946, 2018). "In contrast, thrombocytopenia can also result from LOF THPO or MPL mutations, which cause a complete defect in MPL trafficking to the cell membrane, impaired MPL signaling or stability, defects in the TPO/MPL interaction, or an absence of TPO production." (PMID 28955303, 2017). "Our findings suggest that measurement of serum thrombopoietin concentration provides valuable diagnostic information for differentiating ITP in pregnancy from gestational thrombocytopenia." (PMID 26840092, 2016). "Currently, there are many proposed causes of thrombocytopenia including hypersplenism, antiplatelet antibody formation, or decreased thrombopoietin production." (PMID 27437024, 2016). "Thrombocytopenia of cirrhosis is multifactorial in origin, and decreased activity of thrombopoietin has been identified to be a major cause." (PMID 27800187, 2016). "Antibody development against THPO was associated with thrombocytopenia due to cross-reaction with the endogenous THPO." (PMID 27617228, 2016). "Subspecialist testing—after hematologist consultation—of the blood for thrombopoietin (TPO) may help in assessing TPO deficiency as a cause of thrombocytopenia." (PMID 40095848, 2025). "However, recent studies proposed that reduced circulating thrombopoietin levels and diminished response to thrombopoietin are the primary causes of thrombocytopenia in cirrhosis patients." (PMID 39167137, 2024). "For example, in patients at high risk, prophylactic medication of recombinant human thrombopoietin (rh-TPO) or thrombopoietin receptor agonists (TPO-RA) might be administered to prevent severe thrombocytopenia and to maintain chemotherapy dose intensity." (PMID 37849829, 2023). "That said, one plausible contributory factor that has yet to be explored in the context of HIV-associated thrombocytopenia is the role of anti-thrombopoietin (anti-TPO) antibodies, which could mediate platelet destruction or impair platelet production." (PMID 38005902, 2023). "Her father (B:I‐1) was also thrombocytopenic and recovered from AML, her daughter had a normal platelet count, whereas her son (B:III‐1) had a moderate thrombocytopenia varying between 100 and 130 G/L associated with delta granules impaired secretion and high levels of thrombopoietin." (PMID 36819173, 2023).
Thrombocytopenia (continued). "Monoallelic variants of THPO cause thrombocytopenia with mild symptoms." (PMID 36534659, 2022). "Thus, variants in the formerly classified 5′ UTR of THPO can cause inherited thrombocytopenia, as proven by a functional study." (PMID 36534659, 2022). "In addition, this patient with the THPO variant calls our attention, as the patient showed atypical bone marrow histology from classic inherited thrombocytopenia." (PMID 36534659, 2022). "From a clinical standpoint, thrombocytopenia in liver diseases is often associated with splenomegaly but may also include reduced thrombopoietin released from the impaired liver, and in this way affects platelet production." (PMID 35163004, 2022). "Several mechanisms of COVID-19 associated thrombocytopenia has been suggested: Bone marrow and megakaryocyte suppression due to Inflammatory cytokines, direct viral infection, reduced thrombopoietin can cause thrombocytopenia by destroying progenitors in the bone marrow and reducing platelet." (PMID 34351940, 2021). "Interestingly, COVID-19-associated thrombocytopenia is often accompanied by elevated thrombopoietin levels, which we and others have previously reported." (PMID 34336889, 2021). "In those reports, the anti-THPO antibody was assumed to be the cause of thrombocytopenia." (PMID 32260359, 2020). "In humans with congenital amegakaryocytic thrombocytopenia (CAMT), MPL loss of function mutations, usually in the MPL distal extracellular cytokine receptor homology domain (CRHD), cause thrombocytopenia, an elevated plasma THPO level, and progressive marrow aplasia." (PMID 32479500, 2020). "Thrombocytopenia frequently occurs in chronic liver disease, mainly because of accelerated platelet destruction caused by hypersplenism and hepatocyte damage leading to a decrease in thrombopoietin." (PMID 32190001, 2020). "For example, monoallelic loss‐of‐function of THPO can cause isolated thrombocytopenia and it is likely that further genetic studies may define a broader series of alleles in this pathway leading to a range of diverse phenotypes." (PMID 29191946, 2018). "In patients with advanced hepatitis, thrombocytopenia can be caused by shifts of platelet distribution to an enlarged spleen, platelet destruction due to an immunological mechanism and decreased production of thrombopoietin." (PMID 26622488, 2015). "On the other hand, as liver disease progresses from inflammation to fibrosis and finally to cirrhosis, decreased production of thrombopoietin associated with hepatocellular damage may contribute to exacerbation of thrombocytopenia." (PMID 26088852, 2015). "- 2) Reduced hepatic production of the thrombopoietin (TPO) may be one of the contributing causes of thrombocytopenia during chronic liver diseases." (PMID 21415958, 2009). "Thrombopoietin signalling is important in healthy blood cell development due to its roles in platelet production and maintenance of haematopoietic stem cells, and mutations in the receptor or associated regulators of the pathway manifest clinically as thrombocytopenia or myeloproliferative disease." (PMID 38326297, 2024). "Therefore, thrombocytopenia may be further exacerbated by reduced thrombopoietin production in patients with CIT who also have underlying liver dysfunction." (PMID 39529828, 2024). "Other less common mechanisms of thrombocytopenia in chronic viral hepatitis might be associated with impaired platelet production as a result of suppressed liver synthesis of thrombopoietin, aggravated platelet destruction, and damage to megakaryocytes and platelets by viruses." (PMID 39624338, 2024). "Furthermore, thrombocytopenia in cirrhosis may be caused by the reduction of hematopoietic growth factor thrombopoietin activity in the liver or platelet sequestration in the spleen." (PMID 31931715, 2020). "Patients with grade 3–4 thrombocytopenia were treated with thrombopoietin (TPO) agonist romiplostim." (PMID 41510882, 2026).
Thrombocytopenia (continued). "The thrombocytopenia responded well to thrombopoietin-stimulating agents and immunomodulatory therapy but recurred persistently, even after switching to trastuzumab monotherapy or its subcutaneous formulation." (PMID 41883959, 2026). "Thrombocytopenia results from decreased production of the hormone thrombopoietin (TPO) in the damaged liver and/or increased platelet destruction due to phagocytosis in an enlarged spleen." (PMID 41516346, 2026). "Research using thrombopoietin to expand megakaryocytes and mouse models of thrombocytopenia has accelerated the understanding of platelet biogenesis." (PMID 40141398, 2025). "The mechanism of thrombocytopenia in CKD involves reduced thrombopoietin production, uremic toxins impairing megakaryocyte maturation, and increased platelet destruction." (PMID 41216054, 2025). "The patient’s thrombocytopenia was managed and improved with treatments including recombinant human thrombopoietin (rhTPO) and platelet transfusions." (PMID 41179683, 2025). "In terms of reducing the incidence of grade 3/4 thrombocytopenia, recombinant human thrombopoietin (rhTPO) ranked highest, followed by eltrombopag." (PMID 40766766, 2025). "Thrombocytopenia in WD patients primarily results from hypersplenism secondary to cirrhotic portal hypertension and diminished thrombopoietin production due to hepatic synthetic dysfunction." (PMID 40917366, 2025). "Thrombocytopenia, a universal feature of advanced fibrosis, is a result of splenic sequestration, reduced thrombopoietin, and portal hypertension." (PMID 40647574, 2025). "Possible mechanisms for thrombocytopenia in such cases include splenic sequestration due to congestion, reduced hepatic thrombopoietin synthesis, immune-mediated PLT destruction, and increased PLT consumption caused by hemorrhage or vascular compromise." (PMID 40453929, 2025). "Thrombocytopenia in liver fibrosis is primarily attributed to hypersplenism due to portal hypertension, as well as reduced thrombopoietin production by the liver." (PMID 40361937, 2025). "Thrombocytopenia is a common finding in liver disease, primarily due to splenic sequestration resulting from portal hypertension and decreased thrombopoietin production." (PMID 40429533, 2025). "The available data suggest thrombocytopenia results from a decreased response to thrombopoietin (TPO), affecting both the proliferation and differentiation of megakaryocytes." (PMID 40141398, 2025). "Thrombocytopenia in cirrhosis is frequently multifactorial, most often related to hypersplenism and diminished hepatic thrombopoietin synthesis." (PMID 41409974, 2025). "In advanced stages of the tumour, the tumour itself secretes more thrombopoietin, which increases the platelet count and interacts with cirrhosis and thrombocytopenia." (PMID 39834808, 2024). "Then, stage 3 myelosuppression (mainly thrombocytopenia) occurred, at which point the administration of recombinant human thrombopoietin (TPO) rapidly improved the platelet count." (PMID 38974233, 2024). "He received transfusions of red blood cell suspension and continued treatment for thrombocytopenia with recombinant human thrombopoietin." (PMID 38979408, 2024). "Only 9.4% (n = 5) of the thrombocytopenia cases received platelet transfusions and 3.8% (n = 2) were administered recombinant human thrombopoietin (rhTPO)." (PMID 38562965, 2024). "The patient experienced severe thrombocytopenia, and treatment with thrombopoietin and corticosteroids were ineffective." (PMID 38974233, 2024). "The patient was initially treated with analgesics, nutritional support, empirical anti-infective therapy, subcutaneous denosumab for bone metastasis, and subcutaneous recombinant human thrombopoietin plus interleukin-11 for thrombocytopenia." (PMID 38979408, 2024). "The etiology of thrombocytopenia in cirrhosis is multifactorial and includes platelet splenic sequestration due to PH and decreased thrombopoietin production, resulting in impaired platelet production." (PMID 39296589, 2024).